NDRG1 (N-myc downstream regulated 1)
Diseases named in the same sentence as NDRG1 in open-access papers (continued):
Sharing a sentence is not in itself a finding about the gene and the disease.
tumor (continued). "The expression of NDRG1 (N-Myc downstream regulated gene 4) and DDIT4 (DNA damage–inducible transcript 4), both of which are also implicated in tumor growth, was downregulated by both imeglimin and metformin." (PMID 36639407, 2023). "The bulk of evidence from animal studies has indicated a tumor suppressor role for NDRG1 in colorectal, gastric, nasopharyngeal and renal cell cancers." (PMID 37249826, 2023). "N-Myc Downstream Regulated 1 (NDRG1), a common tumor risk factor, is a powerful immune-related gene in CM and is associated with the ferroptosis pathway." (PMID 37422626, 2023). "After the statistical model was changed in the meta-analysis, results showed a positive correlation between NDRG1 protein expression and tumor grading according to the fixed-effects model (P < 0.01, log OR: 0.87, 95% CI: 0.38–1.37, I2: 57.29%, 3 studies)." (PMID 37858101, 2023). "In our study, through the online data analysis of the GSE14520, ICGC-HCC and TCGA-HCC cohorts, as well as the analysis of collected HCC case data, the results showed that the expression level of NDRG1 in tumor tissues was higher than that in normal tissues." (PMID 37208604, 2023). "Overall, our findings suggest that TGFβ can activate GSK3β to stabilize NDRG1, which results in NF-κB activation as an effector of tumor progression." (PMID 36594086, 2023). "In this sense, post-translational modifications of NDRG1, such as phosphorylation or truncation, are events seen in tumor cells that alter the function and localization of NDRG1 8,11." (PMID 36594086, 2023). "NDRG1 downregulation can promote invasion in vitro, and NDRG1 expression in tumor cells plays an important role in regulating invasion." (PMID 37111248, 2023). "Intriguingly, the state of intracellular iron depletion constitutes a signal to engage tumor suppressive pathways in cancer cells, specifically NDRG1 expression being a common occurrence." (PMID 37894914, 2023). "NDRG1 expression is elevated in esophageal squamous cell carcinoma, wherein expression is correlated with local tumor invasion and poor prognosis." (PMID 37143725, 2023). "All of this evidence indicates that NDRG1 is bidirectional and cell-type-dependent in regulating the cell cycle, suggesting that it has multiple limitations as a target of anti-tumor drugs." (PMID 36770809, 2023). "NDRG1 was barely expressed in the normal tissues and highly expressed in the macrophages of metastatic lymph nodes, portal vein tumor thrombus (PVTT), and primary tumors." (PMID 38235128, 2023). "NDRG1, an α/β-hydrolase, is described to have a tumor suppressive character in PCa and to be involved in the regulation of androgen receptor signaling." (PMID 37671061, 2023). "Comparatively, NDRG1+Macrophage cells were predominantly located in the tumor center, indicating that this subpopulation has a tendency to target the tumor center through chemotaxis." (PMID 38235128, 2023). "A study correlated increased expression of NDRG1 with advanced tumor progression, thus highlighting it as an important prognostic biomarker in invasive BC." (PMID 37970212, 2023). "Specifically, tissue stem cells (defined as tumor cells through tissue sections) exhibited close communication with NDRG1+Macrophages and hepatocytes." (PMID 38235128, 2023). "Based on the results of univariate analyses, expression level of NDRG1, tumor grade, clinical stage and estrogen receptor (ER) status have been associated with overall and disease-free survival times." (PMID 37249826, 2023). "NDRG1 suppression in both instances offers a valuable strategy to potentiate anti-tumour effects, suggesting a promising therapeutic strategy." (PMID 36497221, 2022). "N-myc downstream-regulated gene 1 (NDRG1) is a tumor suppressor with the potential to suppress the proliferation, invasion, and migration of cancer cells." (PMID 35448004, 2022). "NDRG1 has been revealed to act as a tumor suppressor and an oncogene depending on the tumor stage, site of origin and molecular subtype." (PMID 36213122, 2022).
tumor (continued). "Several tumor-suppressive functions of NDRG1 have been reported, including the reduction in cellular motility (invasion/migration), suppression of tumorigenesis (cell growth/stemness conversion), and induction of apoptosis." (PMID 35563887, 2022). "The protein and mRNA levels of the tumor derived from PC-WISP1v1 cells in the xenograft animal model hat indicated that the WISP1 induced CXCL5 but downregulated NDRG1 in vivo." (PMID 36232736, 2022). "N-myc-downregulated gene 1 (NDRG1) interacts with several established tumor signaling pathways; has significant anticancer properties; and prevents cell growth, survival, metastasis, and angiogenesis." (PMID 36713580, 2022). "In recent years, interest in the role of NDRG1 in cancer progression has increased and it is classified as both a pro-tumorigenic and tumour-suppressive protein." (PMID 36497221, 2022). "NDRG1 has been shown to inhibit autophagy, a stress responsive cellular process which is also an important regulator of tumour progression and metastasis." (PMID 36497221, 2022). "Paradoxically, NDRG1 is also a putative tumor suppressor as it is downregulated in several types of cancers, such as prostate, renal, pancreatic, and endometrial cancer, and neuroblastoma." (PMID 35563887, 2022). "Other oncogenic functions of NDRG1 have been reported, including facilitation of tumorigenesis (cell growth/tumor initiation/stemness conversion) and increasing radio-chemoresistance." (PMID 35563887, 2022). "EZH2, GRPEL2, NDRG1, and the clinical factor of tumor size, were included in a nomogram for visualizing a prognostic model of HCC." (PMID 36686830, 2022). "Taken together, it is clear that NDRG1 function in tumour progression or suppression is highly dependent on the tumour-cell type and its differentiation status." (PMID 36497221, 2022). "The enrolled 371 LIHC tumor samples from the TCGA dataset were stratified into high- and low-expression groups according to NDRG1 or NDRG2 median values (cut-off value of 50%), respectively." (PMID 35795037, 2022). "There was a significant difference in the distribution of BMI (P = 0.018), T stages (P = 0.031), pathologic stages (P = 0.016), residual tumor (P = 0.008), and histological grade (P = 0.027) between the high- and low-NDRG1 groups." (PMID 35795037, 2022). "Additional findings also revealed a positive feedback loop between CAFs and the FOXQ1/NDRG1 axis that drives the initiation of HCC in tumour cells." (PMID 36195857, 2022). "Using publicly available datasets, NDRG1 expression was found to be higher in BrM than in the matched primary tumours." (PMID 36497221, 2022). "Previous studies have reported that deregulated expression of NDRG1 affects tumor growth and clinical outcomes of patients with GBM." (PMID 35448004, 2022). "Previous findings have demonstrated that NDRG1 served a major role in inhibiting tumor metastasis via EMT inhibition." (PMID 36293154, 2022). "Caffeic acid phenethyl ester (CAPE), a bioactive compound from propolis, possesses antitumor effect and induces NDRG1 gene expression through the ERK signaling pathway to suppress the tumor growth in certain cancers." (PMID 34662721, 2022). "We also constructed a prognostic nomogram model, which included EZH2, GRPEL2, NDRG1, and the tumor size." (PMID 36686830, 2022). "The induction of apoptosis in PC cells by NDRG1 expression suggested that NDRG1 can restrict cell death evasion and act as a tumour suppressor." (PMID 36497221, 2022). "IHC analysis of these tumours revealed elevated expression of NDRG1, confirming the in vitro studies." (PMID 36497221, 2022).
tumor (continued). "Here, the data analysis from UCSC XENA indicated that the NDRG1 expression had a significant increase in LIHC tumor tissues compared to normal tissues (P <0.001)." (PMID 35795037, 2022). "We demonstrated by Kaplan−Meier analysis that patients with high expression of NDRG1 in specimens of tumor tissue had significantly longer overall survival (OS) than those with low expression of NDRG1." (PMID 35448004, 2022). "N-myc downregulated gene-1 (NDRG1) is often called a metastasis suppressor protein and is found to be expressed in various tumour types." (PMID 36497221, 2022). "Induction of NDRG1 has been directly shown to suppress tumour growth and metastasis in vitro and in vivo in a range of different cancers." (PMID 36497221, 2022). "In analyzing the TCGA dataset with 519 HNSC patients, we found that NDRG1 was overexpressed in tumor tissues, indicating this molecule functions in modulating cancer development." (PMID 35563887, 2022). "N‐myc downstream regulated gene‐1 (NDRG1) plays a role in cell growth, differentiation, signal transduction and is known as a tumor suppressor in various types of cancer including PC." (PMID 35689436, 2022). "It was reported that a marked enhancement of NDRG1 expression resulted in tumor growth suppression; in addition, NDRG1 as a stress responder has been shown to associate with EMT." (PMID 34917147, 2021). "NDRG1 is a stress responsive gene that can have both oncogenic and tumour suppressor roles involved in cellular differentiation, tumour progression and metastasis, hypoxia and DNA damage response." (PMID 34436447, 2021). "Iron-binding ligands, such as DFO and Dp44mT, inhibit the TGF-β-induced EMT via NDRG1 up-regulation, providing a potential therapeutic strategy to inhibit tumor metastasis." (PMID 34572031, 2021). "Pre-metastatic tumours are more likely to be hypoxic; this potentially explains higher levels of NDRG1 expression potentially through HIF-1α." (PMID 33520115, 2021). "The fact that NDRG1 inhibits such a variety of distinct oncogenic pathways is a testament to its potency and versatility as a tumor and metastasis suppressor." (PMID 34572031, 2021). "Carbonic anhydrase IX (Ca-IX) and N-Myc downregulated gene 1 (NDRG1) are known as key regulators of cell hypoxia that promote tumor cell survival." (PMID 34054950, 2021). "From the bioluminescence images, we observed that the tumor xenografts grew remarkably larger in the NDRG1-knockdown group than in the control group." (PMID 34385595, 2021). "NDRG1 played a role in OS cell differentiation and invasion, including inhibited tumor growth by modifying angiogenesis by reducing expression of the angiogenic gene VEGF." (PMID 34099022, 2021). "Together, this would argue for TBX2 interaction with histone-methyltransferases such as was shown for repression of NDRG1 in tumor cells." (PMID 33731112, 2021). "NDRG1 has contradictory roles in cancers, either suppressing metastasis and oncogenesis or promoting tumor growth and metastasis." (PMID 34917147, 2021). "This pleiotropy in NDRG1 function is potentially a reflection of the heterogenous nature of the signaling between tumor cell-types." (PMID 34572031, 2021). "High NDRG1 expression relates to increased cell differentiation signals in various cancer cell lines and the suppression of tumor metastasis." (PMID 33483585, 2021). "NDRG1 also regulated the molecular motor, decreased the migration ability, playing a role of anti-transfer in tumor cells." (PMID 34099022, 2021). "Numerous studies have demonstrated the ability of NDRG1 to suppress tumor growth, angiogenesis and metastasis, processes which are critical for the progression of cancer." (PMID 34572031, 2021). "N-myc downstream-regulated gene 1 (NDRG1) is a key regulator that interacts with many classic tumor signaling pathways, including some molecules downstream of the epidermal growth factor receptor (EGFR)." (PMID 34385595, 2021).
tumor (continued). "The NDRG1 gene is an important stress response protein that responds to a variety of cellular stressors and has a putative function in suppression of tumour metastasis." (PMID 34059695, 2021). "GFP-luciferase-labeled NDRG1-knockdown cells and the corresponding control cells were injected into mice to establish tumor xenografts." (PMID 34385595, 2021). "In our study, HCC cells cultured in native conditions significantly overexpressed NDRG1, which is consistent with HCC tumor biology and its associated resistance to doxorubicin." (PMID 33868588, 2021). "NDRG1 has been reported to exert both oncogenic and tumor-suppressive properties in different tumor types." (PMID 35008802, 2021). "In conclusion, this study disclosed the anti-cancer role of hsa_circ_0003159 in GC through inhibiting proliferation, migration, invasion and xenograft tumor growth and promoting apoptosis, possibly by regulating miR-223-3p and NDRG1." (PMID 32099530, 2020). "This suggests that NDRG1 inhibits tumour proliferation and metastasis by suppressing the expression of genes involved in carcinogenesis." (PMID 32537867, 2020). "Univariate analysis showed NDRG1 expression, tumor grade, disease stage, estrogen receptor (ER) status, and receipt of adjuvant radiation to be associated with OS and DSS." (PMID 33321961, 2020). "In contrast, NDRG1 stimulates carcinogenesis in tumours of the liver, bladder, oesophagus and cervix." (PMID 32537867, 2020). "Sgk1 phosphorylates downstream NDRG1 and is involved in regulating tumor cell proliferation, differentiation, migration, and invasion." (PMID 32106831, 2020). "We found that the level of expression of NDRG1 in tumor tissues predicts the survival outcome of patients with IBC." (PMID 33321961, 2020). "To investigate the biological role of NDRG1 in tumour formation, we introduced two independent NDRG1 shRNAs into 786‐O cells with relatively high expression of NDRG1." (PMID 32537867, 2020). "And TBX2 and TBX3 over-expressions has been elucidated to induce the tumor growth and metastasis, functioning as downstream target gene of Wnt/beta-catenin and pRb pathway through the suppression of p14ARF, p21CIP1, NDRG1 and E-cadherin." (PMID 33447348, 2020). "Our work has highlighted the key role of the NDRG1 in suppressing the proliferation of ccRCC tumour cells." (PMID 32537867, 2020). "In detail, the NDRG1 protein expression was negatively correlated with cancer pT stage (P = .001), pM stage (P = .026) and tumour size (P = .026)." (PMID 32537867, 2020). "N‐myc downstream‐regulated gene 1 (NDRG1) was reported that it can play a key regulatory role in signalling pathways related to tumour progression, especially in tumour metastasis." (PMID 32564470, 2020). "NDRG1 acts as a potent tumor suppressor by inhibiting signaling pathways involved in mediating cell proliferation, migration, invasion, and angiogenesis." (PMID 32550915, 2020). "Higher expression of NDRG1 protein in cancer issues was further confirmed through Mann‐Whitney test (normal: n = 260, tumour: n = 645) (P < .0001)." (PMID 32537867, 2020). "A significant positive correlation was detected between post-NAC GR and Sgk1 or NDRG1 status in the tumor tissues (GR versus." (PMID 32106831, 2020). "In fact, recent studies by Sharma and associates examining prostate cancer cells demonstrated that NDRG1 regulates the expression and glycosylation of EMMPRIN, which is a master regulator of MMP activity in tumor cells and tumor-associated fibroblasts." (PMID 32948029, 2020). "While thiosemicarbazones up-regulate the metastasis suppressor, NDRG1, in adult cancers, it is demonstrated herein for the first time that they induce NDRG1 in all three pediatric tumor cell-types, validating its role as a potential target." (PMID 33334021, 2020). "CCK8 proliferation assay in vitro and subcutaneous tumour formation in mice confirmed the role of NDRG1 in inhibiting tumour proliferation." (PMID 32537867, 2020).
tumor (continued). "We also examined the expression level of NDRG1 mRNA with RT-qPCR and found that NDRG1 level was markedly elevated in 20 HCC tissues as compared with that in paired adjacent non-tumour tissues (P < 0.01)." (PMID 32025371, 2020). "A significant positive correlation was also detected between post-NAC Sgk1 and NDRG1 status of the tumor tissues (P = 0.0009)." (PMID 32106831, 2020). "We further verified that NDRG1 was regulated by both HIF‐1 and −2α in ccRCC cell lines, and the expression level of NDRG1 protein was also positively correlated with HIF‐1/2α in ccRCC tumour tissues." (PMID 32537867, 2020). "Three consecutive tumour sections were obtained from each tumour tissue specimen and were stained by anti‐NDRG1, anti‐HIF‐1α and 2α antibody, respectively, by IHC." (PMID 32537867, 2020). "Hsa_circ_0003159 suppressed proliferation, migration, invasion and xenograft tumor growth but promoted apoptosis by decreasing miR-223-3p and increasing NDRG1 in GC, indicating a novel target for treatment of GC." (PMID 32099530, 2020). "Transwell assay in vitro and mouse tail vein assay suggested that NDRG1 suppressed tumour metastasis." (PMID 32537867, 2020). "Based on the in vitro findings, we examined the effect of NDRG1 on tumor growth and validated its correlation with p21 in xenograft models." (PMID 31831018, 2019). "CCK-8 assay, colony formation assay, flow cytometry, and xenograft model were used to assess the effect of NDRG1 on tumor proliferation in vivo and in vitro." (PMID 31831018, 2019). "Again, studies that exploited traditional GCLs as U87 as model system reported that enforced NDRG1 expression promotes a decrease in tumor vascularization and resistance to anti-angiogenic treatment." (PMID 30538287, 2019). "As NDRG1 is an established tumor growth and metastasis suppressor, iron chelators have been posited as potential inhibitors of metastatic spread." (PMID 31500291, 2019). "NDRG1 has been proved to play a key role in tumor proliferation, metastasis, differentiation, cell adhesion, cell-cycle modulation, and autophagy." (PMID 31831018, 2019). "NDRG1 elicits tumor-suppressive and oncogenic functions depending on the tissue/cell type in which it is expressed." (PMID 30538287, 2019). "We further examined NDRG1 expression in KSHV-positive KS tumor samples and KSHV-negative normal skin tissues by immunohistochemical assays." (PMID 30811506, 2019). "In summary, the authors suggest a novel mechanism by which NDRG1/Cap43 modulates tumor angiogenesis/growth and infiltration of macrophages/neutrophils through attenuation of chemokine expression." (PMID 31561620, 2019). "NDRG1 inhibited tumor proliferation through increasing p21 expression via suppressing p21 ubiquitylation." (PMID 31831018, 2019). "An alternative approach is to restore the expression and function of specific key tumor suppressors, such as NDRG1." (PMID 31739170, 2019). "Recent studies demonstrate that NDRG1 can suppress tumor growth and is related to tumor proliferation; however, the mechanisms underlying these effects remain obscure." (PMID 31831018, 2019). "In our previous studies, we have elaborately revealed the possible mechanisms of and related pathways of NDRG1 in inhibition of tumor metastasis." (PMID 31831018, 2019). "By analyzing the NDRG1 expression of 89 paired CRC samples using IHC, we showed that NDRG1 expression decreased in tumor tissues." (PMID 31831018, 2019). "Considering the role of NDRG1 in tumor progression, therapeutics that can regulate this molecule remains to be developed." (PMID 29467385, 2018). "Studies have shown that iron and copper chelators exhibited their anti-tumor effects through up-regulating NDRG1 level to regress tumor growth and suppress metastasis." (PMID 29467385, 2018).